PTH (parathyroid hormone)
Diseases named in the same sentence as PTH in open-access papers (continued):
Sharing a sentence is not in itself a finding about the gene and the disease.
movement disorder (1 paper, 2025). Neurological conditions resulting in abnormal voluntary or involuntary movement, which may impact the speed, fluency, quality and ease of movement. "For neurologists, when encountering patients presenting with clinical seizures or movement disorders, prompt head computed tomography scans and assessments of serum calcium, phosphorus, and parathyroid hormone levels are crucial to facilitate early diagnosis." (PMID 41431068, 2025).
PTH also shares sentences with these, for which no sentence is quoted: Paget disease (9 papers); dialysis (7); multiple endocrine neoplasia (6); Arrhythmia (5); arteriosclerosis (5); calcium phosphorus metabolism disorders (5); cardiomyopathy (5); diabetic retinopathy (5); neonatal hyperparathyroidism (5); X-linked hypophosphatemia (5); amoebiasis (4); chronic kidney failure (4); developmental delay (4); Hashimoto thyroiditis (4); hematologic malignancies (4); Hepatitis (4); idiopathic infantile hypercalcemia (4); inflammatory bowel disease (4); leishmaniasis (4); cerebral infarction (3); dental caries (3); Down syndrome (3); fibromyalgia (3); glomerulonephritis (3); Granuloma (3); Jansen's metaphyseal chondrodysplasia (3); liver failure (3); nodular goiter (3); nonalcoholic steatohepatitis (3); staphylococcus aureus infection (3).
A further 310 diseases each share a sentence with PTH in 3 papers or fewer.